RGS20 (regulator of G protein signaling 20)
Description:
Inhibits signal transduction by increasing the GTPase activity of G protein alpha subunits thereby driving them into their inactive GDP-bound form. Binds selectively to G(z)-alpha and G(alpha)- i2 subunits, accelerates their GTPase activity and regulates their signaling activities. The G(z)-alpha activity is inhibited by the phosphorylation and palmitoylation of the G protein. Negatively regulates mu-opioid receptor-mediated activation of the G proteins (By similarity).
Synonyms: G(z)GAP; Gz-GAP; RGSZ1; ZGAP1
Tractability: Antibody: its Gene Ontology location is reachable by antibodies, with high confidence. PROTAC: UniProt records ubiquitination sites on it; ubiquitination databases record sites on it; its protein half-life has been measured.
Gene: Protein-coding gene on chromosome 8 (53,851,795 to 53,959,303, forward strand). Ensembl gene ENSG00000147509.
Subcellular location: Membrane; Nucleus; Cytoplasm
Pathways (Reactome):
Signal Transduction: G alpha (i) signalling events; G alpha (z) signalling events
Gene Ontology:
Molecular function: protein binding; GTPase activator activity; GTPase activity
Biological process: G protein-coupled receptor signaling pathway; negative regulation of G protein-coupled receptor signaling pathway; regulation of G protein-coupled receptor signaling pathway
Cellular component: cytoplasm; trans-Golgi network; cytoplasmic side of plasma membrane; plasma membrane; membrane; nucleus
Genetic constraint (gnomAD): Loss-of-function variants: 33 observed, 33.64 expected, observed/expected ratio (o/e) 0.98, 90% interval 0.74 to 1.31. The upper end of that interval is the gene's LOEUF score, 1.31, which puts it in group 5 of 6, group 1 being the genes least tolerant of losing a copy. Missense variants: 453 observed, 466.8 expected, observed/expected ratio (o/e) 0.97, 90% interval 0.9 to 1.05. Synonymous variants: 199 observed, 190.44 expected, observed/expected ratio (o/e) 1.04, 90% interval 0.93 to 1.17.
Homologues: Orthologues: macaque RGS20 (94% identical), chimpanzee RGS20 (93% identical), dog RGS20 (83% identical), mouse Rgs20 (78% identical), rat Rgs20 (78% identical), guinea pig RGS20 (76% identical), tropical clawed frog rgs20 (72% identical), zebrafish rgs20 (66% identical). Paralogues in human: RGS17 (55% identical), RGS19 (54% identical), RGS3 (34% identical), RGS12 (29% identical), RGS4 (29% identical), RGS18 (28% identical), RGS11 (27% identical), RGS5 (27% identical), RGS16 (26% identical), RGS8 (26% identical), RGS21 (25% identical), RGS6 (25% identical), and 11 more.
Diseases named in the same sentence as RGS20 in open-access papers:
RGS20 is named in the same sentence as 20 diseases in open-access papers, as found by Europe PMC text mining. Sharing a sentence is not in itself a finding about the gene and the disease. The quoted sentences say what the papers report.
bladder cancer (3 papers, 2021 to 2024). "In bladder cancer, the high RGS20 expression was associated with unfavorable clinical outcomes." (PMID 35498542, 2022). "Previous studies had explored the associations between RGS family members and bladder cancer risk, including RGS1, RGS2, RGS4, RGS5, RGS6, and RGS20." (PMID 34482807, 2021). "In addition, RGS20 promotes proliferation and migration in bladder cancer through activation of the NF-κB signaling pathway." (PMID 38300336, 2024).
lung adenocarcinoma (3 papers, 2024 to 2025). A carcinoma that arises from the lung and is characterized by the presence of malignant glandular epithelial cells. "Other bimodally expressed genes identified in our analyses, such as FOXM1, MELK, RGS20, and OIP5, have been previously reported to associate with clinical outcomes and play functionally significant roles in lung adenocarcinoma." (PMID 40427178, 2025). "Elevated rgs20 expression was noticed in lung adenocarcinoma (LUAD), lung squamous cell carcinoma (LUSC), and other tumors." (PMID 38431606, 2024). "In this study, we first examined the expression of RGS20 in clinical tumor samples of lung adenocarcinoma and squamous cell carcinoma, and explored the relationship between its expression level and prognosis." (PMID 38431606, 2024). "Additionally, research has demonstrated that SP1 can activate the expression of RGS20 through a super-enhancer to promote the progression of lung adenocarcinoma." (PMID 41304867, 2025).
breast carcinoma (2 papers, 2023 to 2024). "For example, some RGS proteins including RGS4, RGS16, RGS2, RGS6 and RGS17 negatively regulate the progression of breast cancer, whereas RGS20 protein exerts the positive effects on potentiating the carcinogenesis of breast cancer." (PMID 37118788, 2023).
lung carcinoma (2 papers, 2021 to 2024). "These insights support the role of RGS20 as a promising novel molecular marker and a target for future targeted therapies in lung cancer treatment." (PMID 38431606, 2024). "Immunohistochemistry and lung cancer tissue microarray were used to verify the expression of RGS20 between NSCLC patients." (PMID 38431606, 2024).
penile cancer (2 papers, 2022 to 2023). A primary or metastatic malignant neoplasm that affects the penis. "In addition, the increased levels of RGS20 is correlated with tumor progression and unfavorable clinical outcome in penile cancer, where overexpression of RGS20 potentiates penile cancer progression through modulating the activity of PI3K/AKT signaling." (PMID 37118788, 2023). "Regulator of G protein signaling 20 (RGS20) plays an important role in regulating neuronal G protein-coupled receptor signaling; however, its expression and oncogenic function in penile cancer (PC) remains unclear." (PMID 35498542, 2022).
liver cancer (1 paper, 2022). An epithelial or non-epithelial malignant neoplasm that arises from the liver. "The analysis showed that patients with higher RGS20 expression had a worse prognosis (p = 0.005), suggesting that RGS20 may be predictive of survival in liver cancer patients." (PMID 36009801, 2022). "Herein, we investigated the potential role of RGS20 in liver cancer." (PMID 36009801, 2022).
Lymphatic Metastasis (1 paper, 2024). Transfer of a neoplasm from its primary site to lymph nodes or to distant parts of the body by way of the lymphatic system. "Additionally, high RGS20 levels were significantly related to advanced T stage, lymphatic metastasis, and poorer 5-year overall survival rates." (PMID 38431606, 2024).
metastatic melanoma (1 paper, 2008). A melanoma that has spread from its primary site to another anatomic site. "In contrast, the metastatic melanomas express higher levels of genes such as MAGE, GPR19, BCL2A1, MMP14, SOX5, BUB1, RGS20, and more." (PMID 18442402, 2008).
oral cancer (1 paper, 2021). "Evidence also suggested that LINC00084 was involved in the progression of oral cancer as it was highly elevated in the oral premalignant lesions and found to accelerate cell proliferation and invasion of oral cancer cells by regulating miR-365/RGS20 signaling." (PMID 34442351, 2021).
renal carcinoma (1 paper, 2022). A carcinoma arising from the epithelium of the renal parenchyma or the renal pelvis. "Recently, the dysregulated RGS20 expression has been documented in breast, bladder, and renal cancer." (PMID 35498542, 2022). "Recently, RGS20 has been shown to play an important role in the carcinogenesis of breast, bladder, and renal cancer." (PMID 35498542, 2022). "Additionally, the RGS20 expression has been shown to be correlated with immune cell infiltration in renal cancer." (PMID 35498542, 2022).
triple-negative breast carcinoma (1 paper, 2022). An invasive breast carcinoma which is negative for expression of estrogen receptor (ER), progesterone receptor (PR), and human epidermal growth factor receptor 2 (HER2). "In triple-negative breast cancer, the high RGS20 expression is correlated with nodal metastasis and poor clinical outcome." (PMID 35498542, 2022).
cancer (12 papers, 2013 to 2024). A tumor composed of atypical neoplastic, often pleomorphic cells that invade other tissues. "Considering this, herein, we focused our analysis on RGS20, which is solely associated with the occurrence and progression of several cancers, including breast cancer, bladder cancer, oral squamous cell carcinoma, and metastatic melanoma." (PMID 36009801, 2022). "The effect of RGS20 on the malignant phenotype (including uncontrollable cell proliferation, migration, and invasion) of cancer cells has been reported recently; although, the underlying mechanism remains largely unknown." (PMID 35498542, 2022). "Considering the involvement of RGS20 in various cancers, it is surprising that the role of RGS20 in NSCLC remains largely unexplored." (PMID 38431606, 2024). "Another member, RGS20, shares about 62% similarity with RGS17 and has been implicated in the development of various malignant tumors." (PMID 38431606, 2024). "Considering this, we investigated the role of RGS20 as a potential prognostic marker in 28 different cancer types with special emphasis on HCC." (PMID 36009801, 2022). "To investigate the survival potential of RGS20 in other cancer types, we extend our analysis to 28 cancer types." (PMID 36009801, 2022). "Herein, we investigated the role of RGS20 as a potential prognostic marker in 28 different cancers with a particular focus on HCC." (PMID 36009801, 2022). "Of these, KIRC, LIHC, LUAD, and MESO cancers demonstrated poorer survival in the high RGS20 expression group, while OV cancers were observed to have poorer survival in the low RGS20 expression group." (PMID 36009801, 2022). "Regulator of G protein signaling 20 (RGS20) was identified as molecular marker for LUAD for its effect in enhancing cancer cell aggregation, migration, invasion, and adhesion." (PMID 33414898, 2020). "Regulator of G protein signaling 20 (RGS20) is identified as an upregulated factor in many cancers, yet its specific role and the mechanism through which RGS20 functions in NSCLC remain unclear." (PMID 38431606, 2024). "RGS20 has been extensively validated as a participant in cancer initiation and progression." (PMID 38300336, 2024). "However, according to recent reports, RGS20 has been found to be significantly more highly expressed in various cancer tissues than in adjacent normal tissues, such as breast cancer, metastatic melanoma, hepatocellular carcinoma, and bladder cancer." (PMID 37924113, 2023). "An interesting study using overexpression and knockdown of RGS20 in different cancer cell lines showed that it may play a role in the regulation of cancer cell migration and invasion, and even perhaps metastasis." (PMID 36009801, 2022). "Our analysis further supports the putative function of RGS proteins, particularly RGS20, in cancer." (PMID 36009801, 2022). "Furthermore, we also evaluated the survival probability of RGS20 in 28 different cancer types." (PMID 36009801, 2022). "Conversely, RGS20, RPH3A, SGCE, and ZDHHC15 exhibited a substantial downregulation in their expression levels within the corresponding cancer cell lines." (PMID 38300336, 2024). "Actually, a previous study has proven that high expression of RGS20, a member of the RGS family, is correlated with a high percentage of Ki67 expressing cancer cells." (PMID 37529094, 2022). "Interestingly, only five cancers, namely KIRC (p < 0.001), LIHC (p < 0.001), LUAD (p = 0.004), MESO (p = 0.039), and OV (p = 0.048), showed a difference in survival between the high and low RGS20 expression groups." (PMID 36009801, 2022). "Meanwhile, the expression level of RGS20 was elevated in metastatic cancer cells, and then the migration and invasion abilities of NSCLC cell lines (A549 and H1299) were impaired when RGS20 was stably knocked out, suggesting that RGS20 might accelerate the metastasis of tumor cells." (PMID 36793937, 2023).
cancer (continued). "Even though there is still a lack of data on the direct assessment of RGS17, RGS19 and RGS20 in IBD and sporadic CRC based on their impact on opioid activity and involvement in processes in other types of cancers, it seems vital to cover this field in the future studies." (PMID 38203748, 2024).
tumor (10 papers, 2013 to 2024). "Our correlation analysis unveiled numerous significant associations linking the expression levels of RGS20 with distinct immune cell infiltrates, thereby implying its potential regulatory role within the tumor immune microenvironment." (PMID 38300336, 2024). "GSEA analysis revealed some tumor pathways associated with RGS20, namely DNA REPAIR, mTORC1, MYC TARGETS V1 signaling being predominant." (PMID 36009801, 2022). "Here, we observed high RGS20 expression in PC tissues compared to normal/adjacent penile tissues, which was closely associated with tumor stage, nodal status, and pelvic metastasis in our PC cohort." (PMID 35498542, 2022). "This evidence supports that RGS20 was found to be significantly associated with some tumor-related signaling pathways and long non-coding RNAs (lincRNAs) that exhibit oncogenic potential." (PMID 36009801, 2022). "Moreover, we showed that the high RGS20 expression was closely associated with higher tumor stage, nodal/pelvic metastasis, and unfavorable patient survival." (PMID 35498542, 2022). "We noticed a significant decrease in the ratio of p-PKA/PKA and p-YAP/YAP protein levels in the tumor tissues of the RGS20-OE group compared to that of the control group." (PMID 38431606, 2024). "The analysis clearly showed that the expression of RGS20 varied significantly between tumor and normal samples (p = 0.023)." (PMID 36009801, 2022). "We found that RGS20 was strongly upregulated in tumor tissue compared with adjacent normal tissue of HCC patients." (PMID 36009801, 2022). "We first sought to analyze the difference in RGS20 gene expression between normal and tumor tissue samples from the TCGA database." (PMID 36009801, 2022). "Using Cox regression analysis to examine independent HCC survival-related factors, some features including RGS20, age and tumor stage were confirmed." (PMID 36009801, 2022). "Consistent with the in vitro findings, RGS20 depletion suppressed transplanted tumor growth, attenuated PI3K/AKT signaling, and induced apoptosis in vivo." (PMID 35498542, 2022). "In the panel of 421 samples (tumor = 371, normal = 50) and paired samples (tumor = 50, normal = 50), we observed elevated expression of RGS20 in tumor samples compared to the controls using Wilcoxon Rank Sum test." (PMID 36009801, 2022). "For example, the specific mechanisms by which RGS20 activates autophagy, its impact on other tumor behaviors such as invasion, metastasis, and metabolism, and the existence of small molecule inhibitors targeting RGS20, all require further experimental investigations to be addressed in future." (PMID 38431606, 2024). "Since autophagy plays a critical role in various stages of tumor progression, we investigated whether RGS20 promotes cell proliferation by increasing autophagy in NSCLC cells." (PMID 38431606, 2024). "Furthermore, a positive correlation was observed between RGS20 expression levels and the T stage of the tumor as well as cervical lymph node metastasis (N stage)." (PMID 38431606, 2024). "We observed significant inhibition of tumor growth in the RGS20-KD group." (PMID 38431606, 2024). "The high RGS20 expression was significantly related to tumor (T) stage (P = 0.028), nodal status (P = 0.002), and pelvic metastasis (P = 0.019), but not to phimosis (P = 0.106), body mass index (P = 0.347), age (P = 0.502), histological subtype (P = 0.101), or pathological grades (P = 0.379)." (PMID 35498542, 2022). "Furthermore, we noticed that the tumor-promoting activity of RGS20 relies on autophagy." (PMID 38431606, 2024). "Consistent with the in vitro findings, RGS20 depletion attenuated PI3K/AKT signaling activation and suppressed tumor growth in a murine xenograft model." (PMID 35498542, 2022). "Subsequently, we applied RT-PCR to detect the expression level of GAPDH, GNPNAT1, HTATIP2, MFI2, PKP2, RGS20, and CHRDL1 in these 10 tumor tissues." (PMID 35186082, 2022).
tumor (continued). "Therefore, targeting RGS20 might be a useful strategy to abolish PI3K/AKT signaling activation and to suppress tumor development in PC." (PMID 35498542, 2022). "Therefore, RGS20 might be crucial for PI3K/AKT signaling activation and tumor development in PC." (PMID 35498542, 2022).
adenocarcinoma (1 paper, 2024). A common cancer characterized by the presence of malignant glandular cells. "Specifically, RGS20 was more highly expressed in adenocarcinomas than in adjacent noncancerous tissues and exhibited markedly higher expression in squamous lung tissue than that of normal lung tissue." (PMID 38431606, 2024).
RGS20 also shares sentences with these, for which no sentence is quoted: glioblastoma (1 paper); infection (1); lung squamous cell carcinoma (1); non-small cell lung carcinoma (1); substance dependence (1); viral infection (1).